ATF4 (activating transcription factor 4)
Diseases named in the same sentence as ATF4 in open-access papers (continued):
Sharing a sentence is not in itself a finding about the gene and the disease.
tumor (continued). "Because ATF4 deficiency was observed in chemoresistant OS cells, we speculated that ATF4 expression might have a profound effect on the development of tumor resistance." (PMID 31534554, 2019). "While ATF4 activation may be associated with T-cell dysfunction, its role in stress adaptation presents an opportunity for therapeutic intervention—particularly in the tumor microenvironment, where T-cell exhaustion is a major challenge." (PMID 40335738, 2025). "Consequently, pharmacological agents targeting ATF4 or associated pathways may exacerbate mitochondrial dysfunction in tumor cells by inhibiting mitophagy and subsequently induce cell death." (PMID 41020882, 2025). "The extent to which these diverse ATF4-modulated pathways might be involved in control of aging rate, longevity, and the development of neoplastic diseases, which are the most typical cause of death in mice, is at this point a matter for speculation and new experimentation." (PMID 25156122, 2014). "Clinical analyses confirm that ATF4 is enriched in aged tumours and correlates with poor survival and advanced-stage disease." (PMID 41813904, 2026). "Accordingly, neuronal knockout of ATF4 recapitulates the neuroprotection afforded by PERK deficiency, and PERK or ATF4 knockout impairs optic axon regeneration enabled by disrupting the tumor suppressor PTEN." (PMID 41744494, 2026). "In conditions of amino acid starvation, GCN2 acts synergistically with ATF4 to drive tumor neo-angiogenesis by increasing the expression of the key pro-angiogenic factor VEGFA." (PMID 41511286, 2025). "In this study, we introduce a novel strategy that leverages the ATF4 pathway, which is activated by amino acid (AA) scarcity within the tumor microenvironment, as a transcriptional regulator of CAR expression." (PMID 40335738, 2025). "These ATF4-driven metabolic adaptations not only provide energy and biosynthetic precursors necessary for tumor growth but also enable cancer cells to survive and proliferate under metabolically challenging conditions." (PMID 40830338, 2025). "Our experimental results indicate that knocking down ATF4 significantly inhibits the proliferation and migration of tumor cells." (PMID 41451209, 2025). "On the other hand, in some cases, ATF4 expression was found to sensitize tumor cells to therapy-induced cell death." (PMID 39819316, 2025). "Ablation of CHOP or ATF4 in the tumor stroma resulted in reduction of TME-induced CCAAT/enhancer-binding protein-β (C/EBP-β) signaling which led to decreased phospho-STAT3 and IL-6 levels, thereby attenuating the immunosuppressive properties of MDSCs." (PMID 41372991, 2025). "This review explores how ATF4 integrates environmental and cellular stress signals to drive Gln metabolic processes, enabling tumor survival, metabolic reprogramming, and immune evasion." (PMID 40830338, 2025). "In respiratory diseases, the ATF4–lncRNA axis plays a central role in coordinating cellular stress responses, inflammation, and tumor progression." (PMID 40777108, 2025). "TBL2, a novel driver gene, aids tumor adaptation to ERS by upregulating ATF4 and serves as an independent poor prognostic factor in LUAD." (PMID 41407677, 2025). "The interaction between ATF4 and Gln metabolic processes underscores the complexity and adaptability of tumor metabolic reprogramming." (PMID 40830338, 2025). "At the center of tumor(neoplasm) metabolic adaptation lies activating transcription factor 4 (ATF4), a key regulator that orchestrates Glutamine (Gln) uptake, utilization, and redox balance under conditions of nutrient deprivation and oxidative stress." (PMID 40830338, 2025). "Adaptive expression of urea cycle enzymes ARG1/2, OTC, ASL and regulators like NAT10, which stabilizes ATF4 mRNA via ac4C modification to upregulate asparagine synthetase (ASNS) optimizing nitrogen utilization for tumor proliferation." (PMID 41179661, 2025).
tumor (continued). "Representative images of IHC staining for ATF4 showed a significant increase in ATF4 levels in cSCC tumor tissues." (PMID 39870616, 2025). "During tumourigenesis, KRAS‐mutant NSCLC activates ATF4‐mediated integrated stress responses under nutrient stress, sustaining tumour proliferation and progression via KRAS–NRF2–ATF4 signalling." (PMID 40847555, 2025). "Growing evidence indicates that ATF4 interacts with diverse lncRNAs in the digestive system, forming a bidirectional regulatory network that affects tumor growth, inflammation, gluconeogenesis, and treatment resistance." (PMID 40777108, 2025). "Mechanistically, we demonstrated that FADS1 plays a reciprocal role in ER stress and downregulation results in inhibition of tumor growth through induction of PERK/eIF2α/ATF4/ATF3-mediated ER stress response." (PMID 40121894, 2025). "Down-regulating ATF4 expression through gene regulation methods can markedly reduce tumor growth and invasiveness, while also increasing tumor cell sensitivity to various chemotherapy." (PMID 41451209, 2025). "ATF4 acts as a central regulator of amino acid homeostasis in the tumor microenvironment, operating through both direct and indirect mechanisms." (PMID 40830338, 2025). "We found that the regulation of ERO1α was sensitive to KYNU-induced changes in the redox environment, which stimulate the PERK-eIF2α-ATF4 pathway, promote oxidative folding, reduce the number of MFPs, and thereby maintain tumor survival and progression." (PMID 40616124, 2025). "Future research must address tumor heterogeneity and metabolic flexibility to fully harness the potential of ATF4-centered therapies." (PMID 40830338, 2025). "Similar effects are observed with β-apopicropodophyllin, which augments radiation-induced ER stress by activating BiP, PDI, phospho-eIF2α, and ATF4, leading to enhanced apoptosis and delayed tumor progression." (PMID 41476609, 2025). "In conclusion, the ATF4-Gln metabolic axis plays a crucial role in tumor adaptation to metabolic stress, supporting survival, proliferation, and immune modulation." (PMID 40830338, 2025). "Collectively, these findings underscore the pivotal role of ATF4 in maintaining amino acid homeostasis within the tumor microenvironment." (PMID 40830338, 2025). "Our findings reveal that the amino acid-sensing general control nonderepressible-2 kinase (GCN2)/activating transcription factor 4 (ATF4) signaling axis contributes to the upregulation of IL-8 gene expression in glutamine-deprived tumor cells." (PMID 40683891, 2025). "The immunosuppressive function of MDSCs is also diminished by targeting downstream factors of PERK, such as CHOP or ATF4, in different mouse tumor models." (PMID 41372991, 2025). "Promoters of some genes with functions in amino acid transport (Slc7a11, Slc38a1, and Slc43a1) were occupied by ATF4 in DLD-1 MycER tumor cells." (PMID 40542844, 2025). "Intriguingly, restoring ATF4 expression in cSCC cells not only promoted glycolysis but also reversed the anti-tumor effects of METTL1 knockdown." (PMID 39870616, 2025). "Several studies have further shown that ATF4 activation under nutrient or ER stress conditions creates a dependency on glutamine for tumor cell survival and proliferation." (PMID 41209558, 2025). "Although overexpressing Atf4 has a limited impact on tumor sensitivity to in vitro T cell killing, gMettl5 ID8/GC cells with overexpressed Atf4 display reduced T cell‐induced cell death when compared to gMettl5‐EV cells." (PMID 41042068, 2025). "Aspartate can influence mitochondrial respiration and ATP synthesis in tumor cells by modulating mTORC1 activity and upregulating activating transcription factor 4 (ATF4), altering tumor cell activity." (PMID 40863132, 2025). "In osteosarcoma, LINC00963 enhances tumor cell proliferation by sponging miR-320a, thereby activating ATF4 signaling." (PMID 40777108, 2025).
tumor (continued). "ATF4 exhibits dual functions in tumor progression: its hyperactivation promotes tumor survival, whereas under sustained stress, it can also induce apoptosis through the CHOP pathway." (PMID 40830338, 2025). "Environmental factors reciprocally regulate ATF4 expression, forming a feedback regulatory loop that enables tumor cells to survive and proliferate under metabolic stress, nutrient deprivation, and oxidative conditions." (PMID 40830338, 2025). "In CRC, reduced ATF4-dependent expression of asparagine synthetase (ASNS) combined with depletion of extracellular asparagine impairs tumor proliferation." (PMID 40951358, 2025). "The upregulation of ATF4 in cSCC cells counteracted the anti-tumor effect of METTL1 knockdown by enhancing glycolytic capability in cSCC cells." (PMID 39870616, 2025). "ATF4 plays a pivotal role in promoting FA metabolic processes, establishing the necessary metabolic conditions for tumor growth and proliferation." (PMID 40830338, 2025). "Initially, the expression levels of METTL1 and ATF4 in the tumor tissues were examined, revealing a significant enhancement in ATF4 expression in tumors originating from cells harboring the overexpression of ATF4." (PMID 39870616, 2025). "The results of the in vivo tumorigenesis experiments demonstrated that RPL41 inhibits tumor growth and slows the progression of RB by suppressing the expression of ATF4 and ARL5B in RB cells." (PMID 41451209, 2025). "We employed an amino acid-dependent inducible promoter, which triggers ATF4-dependent gene expression to regulate CAR expression in T cells under conditions of amino acid scarcity within the tumor microenvironment." (PMID 40335738, 2025). "In the digestive system, the ATF4–lncRNA axis orchestrates a dynamic stress-adaptive network that regulates key pathological processes such as tumor growth, metabolic reprogramming, ER stress tolerance, and drug resistance." (PMID 40777108, 2025). "Mechanistically, METTL16 promotes the expression and stability of ATF4, thereby suppressing ferroptosis in CC and ultimately accelerating tumor growth." (PMID 39744432, 2025). "Their findings demonstrated that ATF4 overexpression enhances M-CSF secretion, promoting macrophage infiltration into tumor tissues." (PMID 40830338, 2025). "Numerous studies have reported that the sensitivity of tumor cells to ONC201 depends on the induction of DR5 in a manner that is influenced by ATF4 and CHOP." (PMID 41020897, 2025). "This functional duality — shaped by tumor type, microenvironmental stress, and genetic background — positions ATF4 as an emerging therapeutic target." (PMID 40265021, 2025). "In conclusion, the central role of the ATF4-Gln metabolic axis in tumor metabolic processes provides a pivotal target for precision oncology." (PMID 40830338, 2025). "Does the metabolic crosstalk of glutamine between tumor cells and stromal cells (e.g., CAFs) modulate ATF4 activity?" (PMID 40830338, 2025). "Activating transcription factor 4 (ATF4) is a crucial transcription factor that is activated by tumor cells in response to various cellular stress signals." (PMID 41451209, 2025). "Given that ATF4 has been implicated in regulating SLC7A11 and SLC3A2 expression in both tumor and immune cells, we focused on ATF4 for further mechanistic studies." (PMID 41042068, 2025). "These drugs can serve as additional safeguards, providing a switch from tumor microenvironment-regulatable CAR expression to an on/off switch for ATF4-inductable CAR expression while also offering synergistic antitumor effects." (PMID 40335738, 2025). "Instead, our multiomic analyses indicate that METTL5 modulates immune resistance via ATF4, revealing a previously unrecognized pathway linking rRNA methylation to tumor immune evasion." (PMID 41042068, 2025). "The PERK/eIF2α/ATF4 arm, activated by c-Myc and n-Myc, enhances tumor cell survival through the induction of cytoprotective autophagy." (PMID 38509524, 2024).
tumor (continued). "ATF4 knockdown curbed tumor cell proliferation in mice fed either a normal or glutamine‐deficient diet compared to that observed in the corresponding controls." (PMID 38994891, 2024). "This suggests that overexpression of ATF4 can promote the formation of tumour tissues in vivo by inhibiting the ferroptosis of tumour cells." (PMID 38652216, 2024). "Immune cell exposure to a stressed environment in the event of infection, inflammation, and in the tumor microenvironment, results in ATF4 upregulation and activation." (PMID 39288289, 2024). "ATF4 can regulate the differentiation and maturation of macrophages, T-cells, B-cells, and dendritic cells in tumor immunity." (PMID 39288289, 2024). "Cho’s study revealed that RGS2 enhances dormancy cancer cells’ anti-apoptotic ability induced by endoplasmic reticulum stress through modulation of ATF4 expression, correlating with tumor recurrence and chemotherapy resistance." (PMID 38918587, 2024). "The promoting effect of ATF4 on ferroptosis-mediated cell death and tumor angiogenesis can be attenuated by xCT inhibition." (PMID 38601083, 2024). "Tumor presence increased mRNA levels of ATF4 (87.76%, p < 0.001) and GADD34 (301.20%, p < 0.001) in skeletal muscle but only GADD34 mRNA expression was induced in the heart (48.10%, p = 0.033)." (PMID 39294861, 2024). "The inhibition of eIF2α and ATF4 in nutrient-deficient conditions disrupted amino acid homeostasis in multiple stages and molecular subtypes of NSCLC, impairing tumor cell growth and motility." (PMID 38672243, 2024). "Herein, we comprehensively summarized the diverse role of ATF4 in tumors, exploring the clinical implications of targeting ATF4 for anti-tumor strategy." (PMID 38601083, 2024). "Another important nutrient deprivation-responsive pathway is the GCN2-eIF2α-ATF4 axis, which has been reported to be critical for maintaining metabolic homeostasis in tumor cells." (PMID 39462426, 2024). "LSD1 also exerts oncogenic effects on GBM by maintaining the ATF4-dependent integrated stress response, a protective pathway that enables tumor cells to survive under adverse conditions such as hypoxia and nutrient deprivation." (PMID 39765675, 2024). "ATF4 regulates metabolic adaptation, tumor dormancy and autophagy of lung tumor cells in complex manners." (PMID 38601083, 2024). "Asparagine synthetase (ASNS) is an important target gene of ATF4 that modulates protein synthesis, promotes tumor growth and suppresses cell death." (PMID 39261452, 2024). "Consistent with ISR’s role in promoting the biosynthesis of amino acids and nucleotides, the ATF4-folate cycle contributes to tumor growth." (PMID 38462161, 2024). "Next, we explored the in vivo effects of the Keto diet on BACH1/ATF4 function in an MDA-MB-231 xenograft tumor model." (PMID 38838145, 2024). "It is established that chronic ER stress can reduce T cell function by inhibiting the oxidative metabolism in T cells via XBP1 or decreasing T-bet expression via PERK, ATF4 and Chop in tumor-infiltrating CD8+ T cells." (PMID 39408714, 2024). "Inhibition of LSD1 leads to disruption of the ATF4-dependent integrated stress response, impairing the tumor cells’ ability to adapt to environmental stressors." (PMID 39765675, 2024). "ATF4 IF staining was performed with the tumor tissues of each group, and the FP NPs group showed the greatest ERS." (PMID 38553451, 2024). "Our results further demonstrate the potential of ATF4 signaling in tumor development and immunotherapy." (PMID 39139391, 2024). "We provided several lines of evidence demonstrating that HMGA1 plays a critical role in maintaining intracellular redox balance and promoting tumor proliferation by cooperating with ATF4 to activate the transcription of SLC7A11." (PMID 38383528, 2024). "In all cellular models, mouse and human, and regardless the type of tumor, hematopoietic and solid, ATF4 levels were strongly induced upon short AA starvation conditions." (PMID 39013537, 2024).
tumor (continued). "Previous studies indicated that ATF4 signaling was involved in the regulation of tumor cell migration and invasion." (PMID 39090107, 2024). "In the animal study, it is further demonstrated that inhibition of SPHK1 by PF-543 (a SPHK1 inhibitor) and/or inhibition of ATF4 by vemurafenib (a BRAF inhibitor to reduce ATF4 production) can inhibit the growth of TMZ-resistant GBM tumor." (PMID 39090107, 2024). "Phosphorylated eIF2α in turn upregulated the expression of ATF4, a transcriptional activator of genes involved in cell migration and tumor metastasis." (PMID 37834012, 2023). "With enough reduction of MM tumor cells, PIs are thought to enhance the levels of critical osteoblastogenesis-related TFs such as Runx2 and ATF4, and thereby rebuild bone in MM." (PMID 37039914, 2023). "Overall, these finding suggest that ATF4 inhibition is a promising target for diminishing tumor growth and metastasis." (PMID 36739602, 2023). "The worse outcome in patients with high ATF4 expression was consistent with our mouse tumor data, demonstrating that wild‐type tumors had stronger tumorigenicity and metastatic capability than their ATF4 knockout counterparts." (PMID 36739602, 2023). "shL2HGDH#2 cells significantly increased tumor growth as well as the expression of ATF4 target genes, including amino acid metabolism genes, and altered amino acid metabolism compared to the control (shLacZ)." (PMID 36879117, 2023). "CHOP expression in MDSCs was induced by tumour-linked ROS and RNS and it was regulated by the activating-transcription factor-4 (ATF4)." (PMID 36161514, 2023). "To investigate the potential role of ATF4 in tumor growth, we first generated ATF4 knockout (ATF4 KO) and over‐expressing (ATF4 OE) 4TO7 and HeLa cell lines." (PMID 36739602, 2023). "Activation of GCN2 signaling promotes tumor cell survival via phosphorylation of eIF2α which leads to global reduction in cap-dependent translation and activation of ATF4 (activating transcription factor 4)." (PMID 37893077, 2023). "As anticipated, beginning in the third week, the silencing of ATF4 greatly reduced the growth of the AGS tumor in mice when compared to the control group." (PMID 36900220, 2023). "Further studies are necessary to characterize the effect of tumor environmental factors on ATF4-dependent and ATF4-independent serine biosynthesis." (PMID 37187454, 2023). "Regarding the survival strategy, tumor cells also utilize the PERK–eIF2α–ATF4 pathway to reduce the stress resulting from rapid proliferation and nutrient limitation inside a growing tumor mass." (PMID 37591836, 2023). "Remarkably, the ATF4 regulatory pathway is critical for the survival and proliferation of at least two tumour cell types in response to nutrient deprivation." (PMID 37246646, 2023). "Metformin activation of ATF4 induces inhibition of the mitochondrial respiratory chain, which in turn affects tumor growth." (PMID 37326750, 2023). "In summary, these results suggest that L2HG regulates amino acid metabolism by activating ATF4 to promote tumor growth in vivo." (PMID 36879117, 2023). "Our findings demonstrate that around 40%, 80%, and 95% of TJ46, GSC23, and U87 cells, respectively, exhibit ATF4-positive IHC staining in tumor tissues." (PMID 36245009, 2022). "Studies have found that the mRNA level of ATF4 is positively correlated with the resistance of tumor cells to cisplatin." (PMID 35864117, 2022). "Perfusion studies revealed reduced vascular permeability in Atf4Δ/Δ mice, which provides further support for an important role of ATF4 in tumour vascularization." (PMID 35654839, 2022). "Our results showed that overexpression of ATF4 inhibited tumor growth and AR expression in a CAL-148 cell xenograft mouse model." (PMID 35013318, 2022). "(f) Asns expression correlates with ATF4 activity in tumours treated with the docetaxel -L-asparaginase combination." (PMID 36525288, 2022).